CD38 (CD38 molecule)
Diseases named in the same sentence as CD38 in open-access papers (continued):
Sharing a sentence is not in itself a finding about the gene and the disease.
plasma cell dyscrasia (18 papers, 2007 to 2026). "For the treatment of their underlying plasma cell dyscrasia, 72% of patients received a proteasome inhibitor, 56% an alkylating agent, 30% an immunomodulatory drug and 9% an anti-CD38 monoclonal antibody." (PMID 36762300, 2022). "Anti-CD38 therapies (Daratumab, Isatuximab; monoclonal antibodies directed again CD38) are principally used to treat plasma cell neoplasms." (PMID 40075660, 2025). "Daratumumab is an IgG kappa anti‐CD38 monoclonal antibody approved for treatment of plasma cell neoplasms." (PMID 35340637, 2022). "Currently, some specific biomarkers for plasma cell disorders have been studied for both diagnostic and therapeutic purposes: in particular the chemokine receptor 4 (CXCR4) and the differentiation cluster 38 (CD38)." (PMID 33569348, 2020). "CD38 is a transmembrane glycoprotein and in addition to marking mature plasma cells and plasma cell tumors, is a marker for germinal center B-cells." (PMID 31484540, 2019). "In addition to Cyclin D1, the use of markers such as CD138, CD38, and light chain restriction by immunohistochemistry and flow cytometry is critical in characterizing plasma cell disorders." (PMID 40821198, 2025). "CD38 is strongly expressed in both plasma cells and plasma cell tumors." (PMID 31484540, 2019). "Ultimately, the NGS analyses successfully identified two novel antibodies, CD38 and ICAM-1, which are potential candidates for the treatment of plasma cell disorders." (PMID 39631781, 2024). "The IHC profile of plasmablastic lymphoma is relatively similar to that of other plasma cell neoplasms, large B-cell lymphomas, and MALT lymphoma, in which CD30, CD38, CD138, and CD79a are positive; however, CD20 is often negative." (PMID 37046526, 2023). "Indeed, we find a two-log variation between CD38-expression in malignant plasma cell dyscrasias, with median expression in none of the entities reaching the level of normal plasma cells." (PMID 30079070, 2018).
tuberculosis (18 papers, 2010 to 2025). A chronic, recurrent infection caused by the bacterium Mycobacterium tuberculosis. "Further, we and others have demonstrated that high T cell activation, measured by CD38, HLA-DR or Ki-67 expression, is associated with recent M.tb infection, high risk to tuberculosis progression, or on-going tuberculosis disease." (PMID 34526988, 2021). "On the other hand, detailed research on B cells from patients with tuberculosis showed enrichment of CD27 + CD38- memory B cells in lung tissue compared to blood, which was dominated by CD27-CD38- naive and CD27-CD38+ transitional B cells." (PMID 39449326, 2024). "A subset of immature transient CD24++CD38+ B-cells performs diverse regulatory functions, the elevation of which was detected in tuberculosis patients compared to healthy subjects." (PMID 37626620, 2023). "CD38 expression was previously identified as a marker of recent activation seen in M. tuberculosis-specific T-cells from acute patients with tuberculosis." (PMID 37112767, 2023). "In summary, a single measure of HIV-associated immune activation, %CD38+DR+CD8+, was related to pyrazinamide exposure in a cohort of HIV/tuberculosis patients in Botswana." (PMID 29095954, 2017). "Among HIV/tuberculosis patients in Botswana who were ART-naïve at the time of enrollment, we observed that increasing levels of HIV-associated cellular immune activation, as defined by %CD38+DR+CD8+, were associated with decreasing pyrazinamide clearance." (PMID 29095954, 2017). "In a study of patients with TB (n = 60) and asymptomatic contacts (controls, n = 37), we found that TB patients had higher CD38+ T-cell proportions specific for M. tuberculosis protein (PPDMtb), yet total proportions of PPDMtb-specific T-cells were comparable." (PMID 38167987, 2024). "Finally, we characterized the phenotype of IFN-γ-positive T-cell proportions for TAM-TB assay-positive individuals using the marker CD38, which was found to be a feature of M. tuberculosis-specific T-cells during acute tuberculosis." (PMID 37112767, 2023). "Two recent studies from a prospective HIV-tuberculosis cohort treated for tuberculosis, conducted in Uganda showed that TB therapy strongly reduced the expression of CD38 and/or HLA-DR expression on CD8 T while for CD4 cells the reduction in the expression of these markers was less pronounced." (PMID 23840403, 2013). "The results indicated that the frequencies of cytokine-secreting Mtb-specific CD4 T cells with the CD38+CD27– phenotype clearly distinguished individuals with active tuberculosis from those without the disease." (PMID 40406513, 2025). "The study by Ahmed showed Phenotypic changes of MTB-specific T cells are potential surrogate markers for tuberculosis treatment efficacy and can help to discriminate between aTB [profile: CD38(pos), CD27(low)) and latent MTB infection (CD38(neg), CD27(high)], which is consistent with our results." (PMID 36457066, 2022). "Similar results were observed for HIV-tuberculosis patients receiving antiretroviral therapy concurrent with tuberculosis treatment, highlighting the relationship among M. tuberculosis, immune activation and circulating T cell CD8+/CD38+ cells." (PMID 23840403, 2013). "However, the characterization of M. tuberculosis–specific TH1 cells by including markers of recent activation (e.g., CD38, HLA-DR) showed that this approach—termed TAM-TB—is able to identify patients with acute tuberculosis." (PMID 38167987, 2024). "HIV load, CD4 count, and markers of immune activation (CD38 and HLA-DR on CD4 and CD8 T cells) were measured prior to starting, during, and for 6 months after completion of standard 6 month anti-tuberculosis (TB) therapy in 38 HIV infected Ugandans with smear and culture confirmed pulmonary TB." (PMID 20179751, 2010).
tuberculosis (continued). "In addition, only a minor subset of M. tuberculosis-specific T-cells expressed CD38, and although these were only detected in non-BCG-vaccinated contacts, we would not deduce a role of CD38 in recent T-cell activation in the absence of acute tuberculosis." (PMID 37112767, 2023).
Burkitt lymphoma (17 papers, 2011 to 2025). A rare form of malignant mature B-cell non-Hodgkin lymphoma. "Because daratumumab and isatuximab can also target other CD38-positive B-cell malignancies, we included Daudi cells (Burkitt’s lymphoma) and SU-DHL-8 (diffuse large B cell lymphoma) in our study." (PMID 38361357, 2024). "CD38-targeted nanocostructs were proven as potential therapeutic agent in synergy with ultrasound exposure with Burkitt’s Lymphoma cell line, demonstrating their striking effectiveness." (PMID 38353903, 2024). "CM313 exhibits broad but heterogeneous activity against CD38+ cells, including MM, Burkitt’s lymphoma, diffuse large B lymphoma, acute B lymphoid leukemia and acute T lymphoid leukemia cell lines." (PMID 38765013, 2024). "In another study, an anti-CD38 nanobody was used for targeting CD38+ MM/Burkitt lymphoma cells by CAR-NK cells." (PMID 36761751, 2023). "nCD150 mRNA was also detected in primary human tonsillar CD38+ B cells, lymphoblastoid cell line T5–1, Burkitt’s lymphoma cell line BJAB, and Hodgkin’s lymphoma cell line L1236." (PMID 25710480, 2015). "SCID mice challenged with the CD19+ CD38+ human Burkitt’s lymphoma cell line Ramos treated with three daily injections of anti-CD19 BU12-SAP IT or of anti-CD38 OKT10-SAP IT starting at day +7 showed significantly prolonged survival." (PMID 22069735, 2011). "This study identifies CD38 as a potential target for treating paediatric Burkitt's lymphoma." (PMID 39364393, 2024). "The MYC and CD38 status with epidemiological data in 108 patients with suspected Burkitt lymphoma." (PMID 35167621, 2022). "The immunohistochemistry results of laparoscopic biopsy revealed Burkitt lymphoma, characterized by positive expression of CD20, CD79a, CD10, BCL-6, MUM1, and strong positive expression of CD38, c-myc, cyclinD1, and Ki-67 positive index >90%+." (PMID 39993110, 2025). "Our results demonstrate the feasibility of using CD38-specific HLE-nano-BiKEs to efficiently kill MM and Burkitt lymphoma cells." (PMID 35651607, 2022). "A combination of LMO2 negative and CD38 positive is useful for the diagnosis of Burkitt lymphoma." (PMID 31484540, 2019).
myeloid leukemia (17 papers, 2008 to 2025). A clonal proliferation of myeloid cells and their precursors in the bone marrow, peripheral blood, and spleen. "LSCs have been reported to demonstrate a CD34+CD38− phenotype, reflected by the acute immature myeloid leukemia cells KG1a cell line, which expresses high level of CD34 and lacks CD38." (PMID 26557682, 2015). "The suppressive effect mediated by CD38 was alsoobserved in experiments with patient-derived myeloid leukemia cells and with the murine cellline." (PMID 19300526, 2008). "One of the first potentially detected CSCs was CD34+ CD38- myeloid leukemia cells." (PMID 33424978, 2020). "Importantly, TWIST-1 expression in CD34+CD38− immature cells from myeloid leukemia patients (n = 6) was significantly higher compared with cord blood (CB) (n = 5)." (PMID 26023795, 2015). "Lyn and Fgr are the predominant SFKs in myeloid leukemia cells and Lyn binds to CD38." (PMID 23554907, 2013). "Furthermore, in functional xenograft assays, NSG mice engrafted with more immature CD99-positive CD34+CD38− AML LSCs rapidly developed fatal myeloid leukemia, whereas engraftment with CD34+CD38− CD99-negative cells resulted in normal lympho-myeloid development." (PMID 40427525, 2025). "For chronic (K562) and acute (KG-1) myeloid leukemia cells, the CD34, and CD38 antigens were selected for analysis." (PMID 35053549, 2022). "We also examined the ability of our 123b-33bcCAR to eliminate specific cell populations including LSCs (CD123+CD34+CD38−) in the PT3 sample and myeloid leukemia bulk disease (CD34variableCD33+) in the PT4 sample." (PMID 29515236, 2018). "Cancer stem cells were first identified in myeloid leukemia with the cell surface marker combination of CD34+ and CD38-." (PMID 30237856, 2018). "Likewise, depending on the subtype of myeloid leukemia, LSC may reside within the CD34+/CD38− fraction of the clone but also in the CD34+/CD38+ or even in CD34− cell populations." (PMID 25886184, 2015). "Although its expression level was not restricted to the CD34+CD38- fraction, immunotherapy targeting PEPP2 might contribute to eradicating residual LSCs in myeloid leukemia patients." (PMID 26784514, 2016).
cardiac hypertrophy (16 papers, 2016 to 2024). "CD38 is the main hydrolase of intracellular NAD+, and our previous studies showed that CD38 deficiency significantly protected against many cardiovascular diseases, such as cardiac hypertrophy, ischemia/reperfusion injury, and cardiomyocyte senescence." (PMID 37958991, 2023). "Our previous studies showed that CD38 deficiency protected mice from AngII-induced cardiac hypertrophy, ischemia/reperfusion injury, and cardiomyocyte senescence." (PMID 37958991, 2023). "Presently, CD38, associated with sarcoplasmic reticulum membranes, is considered tightly involved in the control of excitation–contraction coupling and heart hypertrophy." (PMID 36557146, 2022). "Suppression of CD38 expression in CD38−/− mice was shown to reduce the cardiac hypertrophy that is associated with chronic exposure to the β-adrenoreceptor agonist isoproterenol." (PMID 28539361, 2017). "It is well known that the intracellular Ca2+ disorder induced by Ang‐II is associated with the development of cardiac hypertrophy, and CD38 as the predominant ADPR‐cyclase is essential for cADPR‐mediated intracellular Ca2+ mobilization." (PMID 28296029, 2017). "In this study, we have examined the effects of CD38 deficiency on the development of cardiac hypertrophy." (PMID 28296029, 2017). "Our previous studies showed that CD38 deficiency protected against cardiac hypertrophy and ischemia/reperfusion injury, alleviated vascular remodeling in hypertension, attenuated diabetic cardiopathy, and delayed D-galactose-induced cardiomyocyte senescence in mice." (PMID 38673941, 2024). "In our previous studies, we found that CD38 deficiency protected against cardiac hypertrophy and ischemia/reperfusion injury, alleviated vascular remodeling in hypertension, attenuated diabetic cardiopathy, and delayed D-galactose-induced cardiomyocyte senescence in mice." (PMID 38673941, 2024). "In the present study, the FOXO3–SOD2‐mediated antioxidative effects were significantly enhanced in CD38 knockdown in H9c2 cells, further demonstrating that the protection of CD38 deficiency on cardiac hypertrophy induced by Ang‐II was consistent with our previous findings." (PMID 28296029, 2017). "CD38 has emerged as a promising therapeutic target for cardio-protection as it has been implicated in the pathogenesis of several cardiovascular diseases including ischemia-reperfusion injury, atherosclerosis, cardiac arrhythmias, myocardial hypertrophy and pulmonary hypertension." (PMID 34680206, 2021). "Moreover, the elevation of NAD+ in CD38‐deficient mice may protect mice from cardiac hypertrophy by enhancing some other NAD+‐dependent enzymes." (PMID 28296029, 2017). "Therefore, our study demonstrated that CD38 deficiency‐mediated SIRT3 activation inhibits cardiac hypertrophy through inhibiting the MAPK/ERK and PI3K/Akt signalling pathways which was induced by the ROS decreasing as well as the direct inhibition from SIRT3–LKB1–AMPK signalling pathway." (PMID 28296029, 2017). "Because CD38 is upstream in this signaling pathway, it seems reasonable to propose that CD38 contributes to these processes and that hearts from CD38−/− mice might also be resistant to cardiac hypertrophy and associated arrhythmias following chronic exposure to β-adrenoreceptor stimulation." (PMID 28539361, 2017). "CD38 also serves as a crucial factor in cardiac hypertrophy by inhibiting SIRT3 expression and activating the Ca2+-NFAT signaling pathway." (PMID 38347953, 2024). "The activation of Sirt3, by increased levels of NAD+ induced by CD38 deficiency, activates AMPK, which suppresses Ang-II-induced cardiac hypertrophy by inhibiting the AKT-glycogen synthase kinase3β (GSK3β)-NFATc pathway." (PMID 36831262, 2023). "The deletion of CD38 fully prevented isoproterenol‐induced death (100% mdx/CD38−/− mice survived) and cardiac hypertrophy." (PMID 35298089, 2022). "Cd38 is related to Angiotensin II activation and pathogenesis of cardiac hypertrophy and hepatic fibrosis." (PMID 34576290, 2021).
cardiac hypertrophy (continued). "CD38 plays an essential role in cardiac hypertrophy since the cardiac hypertrophy was much more severe in wild-type mice compared with CD38 knockout mice." (PMID 31919492, 2020). "Taken together, our results demonstrated that CD38‐mediated cardiac hypertrophy is also involved in activation of Ca2+–calcineurin–NFAT pathway." (PMID 28296029, 2017). "We concluded that CD38 plays an essential role in cardiac hypertrophy probably via inhibition of SIRT3 expression and activation of Ca2+‐NFAT signalling pathway." (PMID 28296029, 2017). "On the hand, CD38 as a widely studied protein in immune system, if it promotes the cardiac hypertrophy through the immune/inflammatory pathways still needs further studies." (PMID 28296029, 2017). "To assess the role of CD38 in regulating cardiac hypertrophy, we used wheat germ agglutinin staining to evaluate cardiomyocyte size." (PMID 28296029, 2017). "In the present study, we investigated the role of CD38 in the development of Ang‐II‐induced cardiac hypertrophy." (PMID 28296029, 2017). "Using Ang‐II‐induced hypertrophic models in vivo and in vitro, we showed that CD38 is a positive regulator of cardiac hypertrophy." (PMID 28296029, 2017). "The results showed that CD38 is a positive regulator of cardiac hypertrophy via inhibition of SIRT3–FOXO3 pathway and activation of Ca2+–calcineurin–NFAT signalling." (PMID 28296029, 2017). "Here, we investigated the roles and mechanisms of CD38 in angiotensin II (Ang‐II)‐induced cardiac hypertrophy." (PMID 28296029, 2017). "The knockout of CD38 gene prevented a hypertrophic response by shutting down the major signalling pathways that induce cardiac hypertrophy." (PMID 28296029, 2017). "Our recent study show that AngII activates an ARC other than CD38 to induce a sustained rise in [Ca2+]i and cardiac hypertrophy." (PMID 26959359, 2016). "CD38 knockout mice were rescued from chronic isoproterenol infusion-induced myocardial hypertrophy, interstitial fibrosis, and decrease in fractional shortening and ejection fraction." (PMID 26959359, 2016). "Evidence suggests that a deficiency in CD38 significantly boosts intracellular nicotinamide adenine dinucleotide (NAD) levels across various tissues, curtails oxidative stress pathways, and ameliorates cardiac hypertrophy and myocardial fibrosis." (PMID 39444553, 2024). "Thus, cADPR-mediated Ca2+ signaling induced by CD38 activation plays a critical role in isoproterenol-induced cardiac hypertrophy and fibrosis." (PMID 36831262, 2023). "Our previous studies showed that CD38-/- mice were resistant to AngII-induced cardiac hypertrophy, significantly protected heart from ischemia/reperfusion injury and high fat diet-induced oxidative stress, and remarkably inhibited AngII-induced smooth muscle cell and cardiomyocyte senescence 11-15." (PMID 34803499, 2021). "Preclinical studies have also shown that CD38 favors angiotensin II-induced cardiac hypertrophy." (PMID 34680206, 2021). "Ang‐II infusion significantly increased the ratio of left ventricle/body weight (LV/BW) by almost 24% in wild‐type mice, but not in CD38‐deficient mice, indicating that CD38 was required for Ang‐II‐induced cardiac hypertrophy." (PMID 28296029, 2017). "Therefore, this study aimed to examine the role of CD38 in Ang‐II‐induced cardiac hypertrophy and to elucidate the mechanisms by which CD38 regulates the hypertrophic process." (PMID 28296029, 2017). "However, the cardiac hypertrophy and fibrosis were much more severe in wild‐type mice compared with CD38 knockout mice." (PMID 28296029, 2017). "Moreover, inhibition of CD38 activity ameliorated ISO-induced cardiac hypertrophy and fibrosis in vivo." (PMID 26959359, 2016). "The recognition of the role of CD38 and other ARCs in maladaptive cardiac hypertrophy may help in the development of new therapeutic strategies to prevent hypertrophic heart diseases." (PMID 26959359, 2016).